VHL (von Hippel-Lindau tumor suppressor)
Diseases named in the same sentence as VHL in open-access papers (continued):
Sharing a sentence is not in itself a finding about the gene and the disease.
clear cell renal cell carcinoma (continued). "Von Hippel–Lindau (VHL) disease is characterized by mutations in the VHL gene, which can induce numerous benign and malignant tumors in different organs, as well as highly vascularized clear cell renal cell carcinomas (ccRCCs)." (PMID 34359798, 2021). "For instance, most clear cell renal cell carcinomas are marked by the loss of VHL tumor suppressor gene function, continuous expression of HIF-1/2α, and maladjusted expression of oncogenic miRNAs." (PMID 32014012, 2020). "We, therefore, overexpressed or knocked down VBP1 protein in VHL-deficient clear-cell renal carcinoma 786-O cells." (PMID 32989053, 2020). "The von Hippel–Lindau (VHL) tumor suppressor gene is well known for causing VHL disease, which involves predisposition to several cancer types, namely clear cell renal cell carcinoma (ccRCC)." (PMID 33333852, 2020). "Clear cell renal cell carcinoma is associated with loss-of-function mutations in the VHL(von Hippel- Lindau) tumor suppressor gene." (PMID 32047543, 2020). "Dysregulation of the von Hippel-Lindau (VHL) gene is closely associated with clear cell renal cell carcinoma (ccRCC), being this one of the most common features in patients with the Von Hippel-Lindau disease." (PMID 31980715, 2020). "Among these, MUC4 has been reported to be associated with exophytic growth of clear cell renal cell carcinoma while VHL linked to a primary oncogenic driver in kidney cancers." (PMID 32714868, 2020). "Loss of von Hippel–Lindau (VHL) protein function can be found in more than 90% of patients with clear cell renal carcinoma (ccRCC)." (PMID 32059438, 2020). "The direct relevance of HIFs for cancer progression has been most clearly demonstrated in clear cell renal cell carcinoma (ccRCC), which in most cases is caused by loss of the von Hippel-Lindau (VHL) tumor suppressor (7, –, 10)." (PMID 31690629, 2020). "Mutational inactivation of VHL is the earliest genetic event in the majority of clear cell renal cell carcinomas (ccRCC), leading to accumulation of the HIF-1α and HIF-2α transcription factors." (PMID 32807776, 2020). "VHL mutations are the most common tumorigenic lesions in clear cell renal cell carcinoma (ccRCC) and result in continued activation of the HIF/VEGF pathway and uncontrolled cancer progression." (PMID 32814829, 2020). "In other familial syndromes, such as Von Hippel-Lindau, patients harbor a VHL mutation, which has been best defined in clear cell renal cell carcinoma, and subsequently are at significant risk of developing renal cancers." (PMID 32066498, 2020). "Often, VHL is mutated in hemangioblastomas, pheochromocytomas, and clear-cell renal carcinomas, illustrating the importance of VHL in the pathogenesis of these diseases." (PMID 31208103, 2019). "Radiogenomic features have been demonstrated to be associated with the luminal B subtype of breast cancer or the VHL gene mutation in clear cell renal cell carcinoma." (PMID 31075839, 2019). "We directly estimate this from the catalog of mutations in the COSMIC database, where we have a reasonably complete description of which point mutations in VHL can be drivers of clear cell renal cell carcinoma." (PMID 29656891, 2018). "In this study we have discovered a novel DNA repair deficiency in VHL-deficient clear cell renal carcinoma." (PMID 29435132, 2018). "Currently it is recommended that, given its rarity, ELST needs to be differentiated from other entities with similar morphologic patterns, particularly other VHL-associated neoplasms such as metastatic clear cell renal cell carcinoma (ccRCC)." (PMID 30340515, 2018). "Germline mutations in VHL result in a syndrome known as von Hippel-Lindau disease, characterized by a high penetrance of clear cell renal cell carcinomas, together with hemangioblastomas of the retina, brain, and spine, and a handful of other tumor types." (PMID 29656891, 2018).
clear cell renal cell carcinoma (continued). "Mutation or promoter hypermethylation of VHL in clear-cell renal carcinoma would give rise to the upregulation of HIF-1α." (PMID 30081604, 2018). "The von Hippel-Lindau (VHL) gene is inactivated frequently in sporadic clear-cell renal cell carcinomas (ccRCCs) by genetic alteration (mutation, loss of heterozygosity, or promoter hypermethylation)." (PMID 30149673, 2018). "Abnormal HIF2α stabilization, through HIF2α gain-of-function or VHL loss-of-function mutations, has been found in pheochromocytomas and paragangliomas, as well as loss of VHL in clear cell renal carcinoma." (PMID 29993038, 2018). "We predict that after chromosome 3p loss in non-carriers, there would only be a few hundred cells with the potential to initiate a future clear cell renal cell carcinoma if a somatic VHL mutation were acquired." (PMID 29656891, 2018). "Inactivation of the VHL tumor suppressor gene is a causal event in the pathogenesis of clear cell Renal Cell Carcinoma (ccRCC), the most frequent subtype of kidney cancer." (PMID 30355451, 2018). "The von Hippel-Lindau (VHL) gene is mutated, deleted, or silenced in 60–80% of human clear cell renal cell carcinomas (ccRCC), the most common type of kidney cancer." (PMID 29435132, 2018). "The incidence of sporadic clear cell renal cell carcinoma is treated as the sum of the same two waiting times plus an additional waiting time for acquisition of a somatic VHL driver mutation." (PMID 29656891, 2018). "Hypoxia-inducible factors (HIFs), angiogenic growth factors, von Hippel–Lindau (VHL) gene mutations, and oncogenic microRNAs (miRNAs) play essential roles in the pathogenesis and drug resistance of clear cell renal cell carcinoma." (PMID 30513765, 2018). "Clear cell renal cell carcinoma accounts for 70%–80% of all kidney cancers, and is known to exhibit very frequent inactivation of the von Hippel-Lindau gene (VHL) as a result of either somatic mutations or epigenetic alterations." (PMID 28846693, 2017). "For example, clear-cell renal cell carcinomas are driven by homozygous loss of VHL, which leads to activation of hypoxia inducible factor (HIF), and subsequently increased transcription of glycolytic enzymes." (PMID 28099114, 2017). "Clear cell renal cell carcinoma (ccRCC), the most common subtype of human kidney carcinomas, is commonly associated with the inactivating mutations of VHL leading to a loss of function of the von Hippel‐Lindau tumour suppressor protein (pVHL)." (PMID 28680592, 2017). "Patients with clear cell renal cell carcinoma (ccRCC) are often diagnosed with both von Hippel-Lindau (VHL) mutations and the constitutive activation of hypoxia-inducible factor-dependent signaling." (PMID 29215599, 2017). "VHL is an established tumor suppressor that is frequently mutated in clear cell renal carcinoma (ccRCC) and functions by facilitating the degradation of HIF1α and pAkt." (PMID 29053101, 2017). "Inherited mutations in the VHL gene cause the VHL disease, an autosomal-dominant neoplastic disease that is associated with various tumour types, including clear cell renal cell carcinomas, haemangioblastomas, pancreatic neuroendocrine tumours and PCC/PGLs." (PMID 28036268, 2017). "For example, von Hippel–Lindau Syndrome leads to the development of clear cell renal carcinoma and is caused by mutations in the VHL gene." (PMID 28408471, 2017). "Clear cell Renal Cell Carcinoma (ccRCC) formation is connected to functional loss of the von Hippel-Lindau (VHL) gene." (PMID 28052007, 2017). "It should be noted that in clinical settings, clear cell renal cell carcinoma (ccRCC) is known to exhibit significant loss of mitochondrial proteins and often shows somatic VHL mutation, resulting in constitutive HIF-α subunit stabilization." (PMID 28060746, 2017). "While there has been limited evidence of a link between molecular pathways, BAP1 mutation has coincided with VHL mutation in clear cell renal cell carcinoma (ccRCC)." (PMID 29085180, 2017).
clear cell renal cell carcinoma (continued). "VHL is a key tumor suppressor that is mutated in Von Hippel-Landau disease, a hereditary cancer predisposition syndrome that often manifests as clear-cell renal carcinoma (ccRCC)." (PMID 29053101, 2017). "The von Hippel-Lindau (VHL) is deficient in ∼70% of clear-cell renal cell carcinomas (ccRCC), which contributes to the carcinogenesis and drug resistance of ccRCC." (PMID 28643803, 2017). "Clear cell renal cell carcinoma (ccRCC), the most common form of Kidney cancer, is characterized by frequent mutations of the von Hippel-Lindau (VHL) tumor suppressor gene in ~85% of sporadic cases." (PMID 28812986, 2017). "Clear cell renal cell carcinoma (ccRCC) is characterized by loss of function of the von Hippel–Lindau tumour suppressor (VHL) and unrestrained activation of hypoxia-inducible transcription factors (HIFs)." (PMID 27774982, 2016). "About 70 % of clear cell renal cell carcinoma (ccRCC) have VHL mutations with varying impact on pVHL function." (PMID 27530247, 2016). "In order to demonstrate USP9X negatively regulates pVHL in clear cell renal cell carcinoma (ccRCC) which is a VHL disease associated neoplasm, USP9X was knocked down in 786-0 cells stably expressing HA-tagged pVHL." (PMID 27517496, 2016). "Many studies have demonstrated the role of VHL in clear cell renal carcinoma where the VHL gene can be inactivated by mutations, leading to stabilization of HIF-1 and its subsequent transcription of target genes." (PMID 25988385, 2015). "Inactivation or mutation of the VHL gene causes various tumors, including clear cell renal cell carcinoma (ccRCC)." (PMID 25749518, 2015). "Germline mutations in the von Hippel-Lindau (VHL) tumor suppressor gene predispose individuals to clear cell renal carcinomas, hemangioblastomas, and pheochromocytomas." (PMID 25729330, 2015). "Clear cell Renal Cell Carcinoma (ccRCC) is due to loss of von Hippel–Lindau (VHL) gene and at least one out of three chromatin regulating genes BRCA1-associated protein-1 (BAP1), Polybromo-1 (PBRM1) and Set domain-containing 2 (SETD2)." (PMID 26452128, 2015). "In the kidney, VHL-deficient cells give rise to renal clear cell carcinoma which can metastasize into brain and spinal cord." (PMID 28326266, 2015). "PAG1 attracted our attention because it had been reported to be overexpressed in clear cell renal cell carcinoma (ccRCC) which is frequently associated with loss of VHL function and constitutive HIF-2α overexpression." (PMID 26007655, 2015). "VHL inactivation is the most established molecular characteristic of clear cell renal cell carcinoma (ccRCC), with only a few additional genes implicated in development of this kidney tumor." (PMID 26169495, 2015). "Whereas HIF-2α acts as a tumor suppressor in glioma, non-small cell lung cancer, and hepatocellular carcinoma, it drives tumorigenesis and growth of VHL-deficient renal clear-cell carcinoma." (PMID 25893706, 2015). "VHL plays a pivotal role in ccRCC tumorigenesis and is mutated or silenced in more than half of sporadic clear cell renal cell carcinomas." (PMID 24849932, 2014). "Mutations in the VHL gene occur in various inherited tumors associated with VHL disease as well as in some sporadic tumors such as clear-cell renal carcinomas, hemangioblastomas and sporadic pheochromocytoma." (PMID 25490036, 2014). "We perform whole exome sequencing on four clear cell renal cell carcinomas removed from both kidneys of a patient with a germline VHL mutation." (PMID 25159823, 2014). "TMEM115 has been reported to have reduced expression in renal clear cell carcinomas and other VHL-deficient tumors and to exhibit Golgi localization." (PMID 24806965, 2014). "These cysts are notable for biallelic VHL inactivation in renal tubular epithelial cells; whereas, clear cell renal cancer is additionally characterized by mutations in genes involved in the PTEN-mTOR pathway." (PMID 25589003, 2014).
clear cell renal cell carcinoma (continued). "Somatic mutations or loss of expression of tumor suppressor VHL happen in the vast majority of clear cell Renal Cell Carcinoma, and it’s causal for kidney cancer development." (PMID 24260413, 2013). "The combinations of genetic alterations that cooperate with von Hippel–Lindau (VHL) mutation to cause clear cell renal cell carcinoma (ccRCC) remain poorly understood." (PMID 23606570, 2013). "Clear cell renal cell carcinoma (ccRCC) is the most common histological subtype of kidney cancer and is often characterized by mutations or deletions of the Von Hippel Lindau (VHL) tumour suppressor gene." (PMID 23785518, 2013). "It is now known that the inactivation of the VHL tumor suppressor gene plays a causal role in the pathogenesis of clear cell renal cell carcinomas (ccRCC)." (PMID 24260413, 2013). "The tumor suppressor gene, Von Hippel-Lindau (VHL), is frequently mutated in the most common form of kidney cancer, clear cell renal cell carcinoma (CCRCC)." (PMID 23178531, 2012). "Somatic mutations or reduced expression of the von Hippel-Lindau (VHL) tumor suppressor occurs in the majority of the clear cell renal cell carcinoma (ccRCC) and is a causal factor for the pathogenesis of ccRCC." (PMID 21949687, 2011). "In von Hippel-Lindau (VHL) disease, germline mutations in the VHL tumor suppressor gene cause clear cell renal carcinomas, hemangioblastomas, and pheochromocytomas." (PMID 19602254, 2009). "von Hippel-Lindau (VHL) disease arises from heterozygous germline mutations in the VHL tumor suppressor gene, which resides on chromosome 3p25, and is characterized by clear cell renal carcinomas, hemangiomas, pheochromocytomas, as well as other tumor types." (PMID 17598890, 2007). "Mutational inactivation of the von Hippel-Lindau (VHL) tumor suppressor gene has been linked to hereditary as well as sporadic clear cell renal carcinomas." (PMID 17598890, 2007). "Hypoxia-inducible factor 1α stabilisation results from mutations in the von Hippel–Lindau (VHL) gene, which occur in the majority of clear cell renal cancers." (PMID 12865914, 2003). "Somatic von Hippel-Lindau disease tumour-suppressor gene (VHL) mutations are frequently detected in sporadic clear cell renal cell carcinomas (RCC), and germline VHL mutations are the commonest cause of familial clear cell RCC." (PMID 9652757, 1998). "Clear cell renal carcinoma (ccRCC) and von Hippel-Lindau (VHL)-associated tumors arise due to dysregulation of the VHL/HIF pathway resulting from loss or inactivation of the VHL tumor suppressor gene, leading to constitutive activation of hypoxia-inducible factors (HIFs)." (PMID 42306392, 2026). "Clear cell renal cell carcinoma (ccRCC) is driven by von Hippel-Lindau (VHL) tumor suppressor loss and persistent activation of hypoxia-inducible factors (HIFs), which coordinately regulate angiogenesis, metabolic reprogramming, redox balance, and tumor-immune interactions." (PMID 42196561, 2026). "Especially in cellular tumors, the differential diagnosis between HB and metastatic clear cell renal cell carcinoma (ccRCC) is quite challenging if based solely on morphology, and it can be even more complex due to the fact that ccRCC is often associated with vHL mutation and/or VHL syndrome." (PMID 39807616, 2025). "VHL loss has detrimental consequences on clear cell renal carcinoma cell reprogramming." (PMID 41301058, 2025). "Tumors from 80% of clear cell renal cell carcinoma (ccRCC) patients have mutations in the VHL gene." (PMID 39468223, 2025). "For example, HIF-1α was reported to remain relatively high even in a richly vascularized (oxygen rich) microenvironment in clear cell renal cell carcinoma (ccRCC, sporadic ccRCC cases are often caused by aberrations in the VHL (encode von Hippel–Lindau tumor suppressor protein) gene)." (PMID 39757165, 2025).
clear cell renal cell carcinoma (continued). "Germline mutations that inactivate the VHL tumor-suppressor gene cause von Hippel–Lindau disease, which predisposes individuals to the most common form of kidney cancer, clear-cell renal cell carcinoma (ccRCC), as well as various other tumors such as hemangioblastomas and paragangliomas." (PMID 40178040, 2025). "Clear-cell renal cell carcinoma (ccRCC) is characterized by a pseudohypoxic intracellular state and genetic abnormalities, including mutation of the von Hippel–Lindau (VHL) tumor suppressor gene whose inactivation leads to stabilization of hypoxia-inducible factors (HIF1s)." (PMID 40332447, 2025). "Clear cell renal carcinoma (ccRCC) is the most common subtype of renal cell carcinoma, typically characterized by the loss of function of the tumor suppressor gene von Hippel–Lindau (VHL) in the majority of cases." (PMID 39451551, 2024). "However, in more than 90% of sporadic clear cell renal cell carcinomas, loss of chromosome 3p, which harbors tumor suppressors VHL on 3p25 and PBRM1, BAP1, and SETD2 on 3p21, is an established occurrence." (PMID 39281855, 2024). "Inactive von Hippel-Lindau (VHL) was associated with metabolic reprogramming in clear cell renal cell carcinoma (ccRCC), and it was reported that carcinogenic positive feedback exists between histone lactylation caused by inactive VHL in ccRCC and platelet-derived growth factor receptor β (PDGFRβ)." (PMID 39502530, 2024). "Notably, VHL patients are at increased risk for developing clear cell renal cell carcinoma and pheochromocytoma." (PMID 39272694, 2024). "According to this methodology, chromosome 3p loss with concurrent chromosome 5q gain may occur during childhood to adolescence and the remaining VHL allele may be lost after this event in sporadic clear cell renal cell carcinoma." (PMID 37182269, 2023). "Similarly, in clear cell renal cell carcinoma, the increase in tumor aggressiveness was found to correlate with reduced expression of VHL identifying VHL downregulation as a risk factor for worse patient overall survival." (PMID 36036061, 2023). "Per this study, evidence for the expression of hemangioblast proteins in different types of VHL-associated tumors is provided, including cerebellar and spinal hemangioblastomas, clear cell renal cell carcinomas, pheochromocytomas, pancreatic neuroendocrine tumors, and paragangliomas." (PMID 37174017, 2023). "The microscopic diagnosis was a malignant epithelioid neoplasm with clear cell and rhabdoid features, and molecular testing revealed pathogenic variants in BAP1 and VHL, resulting in a post-mortem diagnosis of metastatic clear cell renal cell carcinoma (mccRCC)." (PMID 37844295, 2023). "Von Hippel-Lindau (VHL) disease is an autosomal dominant inherited cancer syndrome caused by germline mutations in the VHL tumor suppressor gene, characterized by the susceptibility to a wide array of benign and malign neoplasms, including clear-cell renal cell carcinoma." (PMID 36358771, 2022). "The Lindau syndrome (VHL) gene mutation is the most common cause of renal clear cell carcinoma." (PMID 35096263, 2022). "The germline VHL mutations have been linked to VHL disease, which is an inheritable condition leading to retinal and central nervous system hemangioblastomas, clear cell renal cell carcinomas, pheochromocytomas, pancreatic neuroendocrine tumors and endolymphatic sac tumors." (PMID 36451132, 2022). "Mutations of VHL tumor suppressor gene are responsible for the development of a variety of tumors including clear cell renal cell carcinoma (RCC), pheochromocytomas, endolymphatic sac tumors, and pancreatic cysts, even though only loss of VHL tumor suppressor gene is not enough to induce RCC." (PMID 34884197, 2021). "The significance of this is unclear, but HIF-1α has been reported to act as a tumour suppressor in VHL-associated renal clear cell carcinoma, and it may be that HIF-1 also has a tumour suppressive role in this context." (PMID 34658364, 2021).